ACTB (actin beta)
Diseases named in the same sentence as ACTB in open-access papers (continued):
Sharing a sentence is not in itself a finding about the gene and the disease.
ciliopathies (1 paper, 2025). "The study found that SPAG6, TRAF3IP1, IFT22, and KIF3B showed lower correlations with ciliopathies, while IFT172, TTC21B, CEP290, ACTB, and DYNC1H1 were highly correlated." (PMID 40432967, 2025).
clear cell renal carcinoma (1 paper, 2017). A malignant epithelial neoplasm of the kidney characterized by the presence of lipid-containing clear cells within a vascular network. "Ppia, was optimal candidate (along with PRS13) in clear cell renal carcinoma as compared to classical genes such as ACTB, GAPDH, 18s or B2m." (PMID 28591185, 2017).
Desminopathy (1 paper, 2024). "The common hub genes in desminopathy and titinopathy were cytoskeleton- (ACTB, ANXA2), and ECM-related (CD44)." (PMID 39239540, 2024).
dystonia-deafness syndrome (1 paper, 2018). "Thus, we propose that the dystonia-deafness syndrome caused by ACTB p.Arg183Trp heterozygosity can be explained by specific functions of beta-actin that are compromised in different cell types and cellular functions at different developmental stages." (PMID 29788902, 2018).
endometrioid carcinomas (1 paper, 2024). "Eight common proteins were identified between normal endometrium with diploid endometrioid carcinomas and diploid with aneuploid endometrioid carcinomas, namely ACTB, ATP5B, ATP5E, INS, IVNS1ABP, LMNB, PLS1, and VIM." (PMID 39194522, 2024). "Comparison between normal endometrium and diploid endometrioid carcinomas identified 19 proteins and interaction networks, with VIM, ACTB, and NFκB being the most relevant proteins." (PMID 39194522, 2024). "Comparison between diploid and aneuploid endometrioid carcinomas identified 20 proteins, with VIM, GRB2, and ACTB highlighted as the most important network nodes." (PMID 39194522, 2024).
Fabry disease (1 paper, 2020). Fabry disease (FD) is a progressive, inherited, multisystemic lysosomal storage disease characterized by specific neurological, cutaneous, renal, cardiovascular, cochleo-vestibular and cerebrovascular manifestations. "The results showed interactions between ACTB and PFN1-NOS3 or eNOS as well as the complement pathway suggesting their potential role as biomarkers of the molecular pathology of Fabry disease: ACTB is involved in the eNOS regulation, and PFN1 participates in actin polymerization as well as VCL." (PMID 33138098, 2020).
generalized dystonia (1 paper, 2018). "In conclusion, this is the seventh patient reported to date with DDS caused by the ACTB p.Arg183Trp variant and is one of four patients who have survived the associated severe, generalized dystonia, due to substantial improvement from pallidal stimulation." (PMID 29788902, 2018). "Deep brain stimulation of the internal pallidum bilaterally should be strongly considered to treat generalized dystonia in ACTB p.Arg183Trp carriers." (PMID 29788902, 2018).
glomerular diseases (1 paper, 2016). "We checked the most important 4 genes YWHAZ, ACTB, APC, and FYN in differentially regulated genes list and found that they were all regulated in at least 3 glomerular diseases, especially the APC was regulated in all 5 glomerular diseases." (PMID 27227331, 2016).
HIV-1 infection (1 paper, 2019). The type species of lentivirus and the etiologic agent of acquired immunodeficiency syndrome (AIDS). "Additionally, ACTB and ACTG1 are known to inhibit viral assembly and production, and THBS1 is known to inhibit HIV-1 infection." (PMID 30626383, 2019).
Hypercholesterolemia (1 paper, 2022). An increased concentration of cholesterol in the blood. "Interaction analysis showed that ACTB formed the hub of the revealed network, being involved in many interactions with other accessory proteins (e.g., with upregulated CAP1, WDR1, GSN, RHOA, and ARPC1A), suggesting myocardial cytoskeleton rearrangement in response to hypercholesterolemia." (PMID 35806390, 2022).
hypertensive nephropathy (1 paper, 2021). Kidney damage that results from chronically elevated blood pressure; complications include glomerular damage resulting in proteinuria and hematuria. "Expression variability of 4 candidate genes (YWHAZ, SLC4A1AP, RPS13 and ACTB) was further examined by qPCR in biopsies from patients with hypertensive nephropathy (n = 11) and healthy controls (n = 5)." (PMID 34882702, 2021).
ischemia (1 paper, 2022). A hypoperfusion of the BLOOD through an organ or tissue caused by a PATHOLOGIC CONSTRICTION or obstruction of its BLOOD VESSELS, or an absence of BLOOD CIRCULATION. "Sixty days after hHTX, GATA2 expression was significantly downregulated in grafts subjected to 12 h of ischemia, but this effect was reversed when donors had received S-NO-HSA (−6.00 ± 0.45 vs. −7.188 ± 0.5; 12 h-S-NO-HSA-hHTX vs. 12 h-control-hHTX: p = 0.0008; normalized expression to ACTB)." (PMID 35497886, 2022).
keratoconus (1 paper, 2025). A degenerative, structural disorder of the eye, characterized by a cone-shaped protrusion of the cornea. "Additionally, the patient with ACTB mutation presented with keratoconus." (PMID 40488176, 2025).
Kidney Cyst (1 paper, 2019). Abnormal fluid filled sac within the kidney, either acquired or congenital. "ACTB loss-of-function mutations result in a pleiotropic developmental disorder, including unilateral renal agenesis, pelvic kidney, and kidney cysts, whereas there are few reports about the effect of the common variants at ACTB on the renal function." (PMID 31396261, 2019).
kidney failure (1 paper, 2024). An acute or chronic condition that is characterized by the inability of the kidneys to adequately filter the blood. "These implicate that the disorder of cell cycle and immune system may play pivotal signaling roles, with the interlinks between ACTB and TLR4 potentially driving the common pathogenesis in both heart and kidney failure." (PMID 39351221, 2024).
liver cirrhosis (1 paper, 2023). "In summary, we found ACTB, TAGLN, VIM and SOX9 are the potential key biomarkers of liver cirrhosis." (PMID 36725885, 2023).
liver failure (1 paper, 2024). A liver disease characterized by the liver losing or has lost all of its function. "Other important disease-relevant processes such as liver failure (LCAT, LDHA), complement activation (C3) and tissue damage (MB, H2AC17, ACTB) were also represented by the ML features." (PMID 39681038, 2024).
male infertility (1 paper, 2025). The inability of the male to effect fertilization of an ovum after a specified period of unprotected intercourse. "Notably, several SNPs associated with parental interaction effects in the ART sample mapped to genes previously implicated in male infertility, including ACTB, FSCN1, and RNF216." (PMID 41325449, 2025).
meningitis (1 paper, 2022). A disorder characterized by acute inflammation of the meninges of the brain and/or spinal cord. "Future research should focus on revealing the mechanism of action of HSPD1/ACTB inhibitors, which have great potential for treating meningitis if they can be ensured to be safe in treated animals and humans." (PMID 35805155, 2022).
migraine (1 paper, 2021). "In the migraine patients and controls, the expression data of the CHRNA7 gene compared to the ACTB control gene, and the relationship between copy number changes in the gene were examined; moreover, median and p values were calculated." (PMID 34563047, 2021).
multinodular goiter (1 paper, 2019). Nodular goiter characterized by more than one discrete tissue mass. "The expression characteristics of 12 candidate reference genes (GAPDH, ACTB, HPRT1, TBP, B2M, PPIA, 18SrRNA, HMBS, GUSB, PGK1, RPLP0, and PGM1) were assessed by qRT-PCR in 45 thyroid tissue samples (15 papillary thyroid carcinoma, 15 paired normal tissues and 15 multinodular goiters)." (PMID 31645594, 2019).
nasal polyps (1 paper, 2018). "In intact RNA, they found that the genes for hydroxymethyl-bilane synthase (HMBS) and succinate dehydrogenase complex, subunit A (SDHA) in CRS, and ACTB and TBP in nasal polyps were the most stable among nine candidate reference genes analysed using geNorm." (PMID 29371606, 2018).
neuroendocrine tumors of the (1 paper, 2016). "In the present study, ACTB, CDKN1B, GAPDH, GRB2, RHOA and SDCBP were identified as suitable reference genes in neuroendocrine tumors of the lung." (PMID 27802291, 2016). "ACTB, CDKN1B, GAPDH, GRB2, RHOA and SDCBP are potent reference genes in neuroendocrine tumors of the lung." (PMID 27802291, 2016).
osteonecrosis of the (1 paper, 2022). "The stability of ACTB is significantly downregulated in bone marrow-derived mesenchymal stem cells of the osteonecrosis patients." (PMID 35035862, 2022).
ovarian mucinous tumors (1 paper, 2014). "With M values less than 1.5, HRPT1, RPL13A, ACTB, TBP, PBGD, and RPLP0 were recommended as a dependable normalizing combination for ovarian mucinous tumors." (PMID 24776823, 2014).
ovarian serous tumor (1 paper, 2014). A benign, borderline, or malignant epithelial tumor of the ovary characterized by the presence of neoplastic epithelial cells that, in well differentiated tumors, resemble the epithelial cells of the fallopian tube and, in poorly differentiated tumors, show anaplastic features. "ACTB, PPIA, RPL13A, RPLP0, TBP, and B2M achieved high expression stability, which suggested that they were adequate for normalizing gene expression data among ovarian serous tumors." (PMID 24776823, 2014).
pancreatic adenocarcinoma (1 paper, 2021).
periodontitis (1 paper, 2024). An acute or chronic inflammatory process that affects the tissues that surround and support the teeth. "Spatial transcriptomics revealed significant upregulation of ACTB, GSTO1, RAB1B, HBB, DMKN, and CTSZ in basal epithelial cells during periodontitis." (PMID 39769019, 2024).
post-traumatic stress disorder (1 paper, 2015). An anxiety disorder precipitated by an experience of intense fear or horror while exposed to a traumatic (especially life-threatening) event. "In other studies, while the GAPDH, B2M and ACTB genes were shown to be reliable reference genes in peripheral blood mononuclear cells in post-traumatic stress disorder patients, β-actin and TUBB1 were used as the reference genes in human skin fibroblasts after UVB irradiation." (PMID 25271263, 2015).
prostate tumour (1 paper, 2016). "ACTB and GAPDH were chosen as they were already used for CLDN gene expression analyses in canine prostate tumour and mammary tissue and tumour derived cell lines." (PMID 27690019, 2016).
pulmonary TB (1 paper, 2025). "To identify the most stable HKGs for analyzing material from patients with pulmonary TB, we selected eight genes—ACTB, B2M, GAPDH, HPRT1, PPIA, RPL13A, YWHAZ and UBC—that are most commonly employed as reference genes in clinical studies." (PMID 41303702, 2025). "In clinical research—including studies of pulmonary TB—the genes GAPDH, ACTB, B2M or ribosomal RNA genes are most frequently chosen as reference genes." (PMID 41303702, 2025).
renal agenesis (1 paper, 2019). Renal agenesis (RA) is a form of renal tract malformation characterized by the complete absence of development of one or both kidneys (unilateral RA or bilateral RA respectively), accompanied by absent ureter(s). "Because ACTB loss-of-function mutations result in renal agenesis and impairment, the study of the common variants at ACTB and CKD as well as eGFR would be deserved." (PMID 31396261, 2019).
rotator cuff tears (1 paper, 2015). "HPRT1+TBP+ACTB seems to be the best combination of reference genes for the analysis of involving different tendon samples of individuals with rotator cuff tears." (PMID 25768100, 2015). "Although the gene stability data were not provided, GAPDH and ACTB have been used as a reference genes in the study of mRNA regulation in human rotator cuff tear." (PMID 25768100, 2015). "In this study, we assessed the suitability of six reference genes frequently reported in the literature (18S, ACTB, B2M, GAPDH, HPRT1 and TBP) using tendon samples from individuals with and without rotator cuff tear by analyzing gene stability with four software packages." (PMID 25768100, 2015).
sarcoidosis (1 paper, 2008). Sarcoidosis is a multisystemic disorder of unknown cause characterized by the formation of immune granulomas in involved organs. "Finally, to demonstrate effect of traditional (ACTB/GAPDH) and novel (PSMB2/RPL32) reference genes as denominators, expression of two cytokines known associated with sarcoidosis was investigated in sarcoid BAL cells." (PMID 18671841, 2008). "Similar, when CCL2 mRNA levels were expressed as a ratio to ACTB (1.00 ± 0.85; p = 0.46) or to GAPDH (1.37 ± 0.98; p = 0.43), there were not significant differences in mRNA levels in BAL cells between sarcoidosis patients with chest radiographic stage 2 and stage 1 patients." (PMID 18671841, 2008).
schistosomiasis (1 paper, 2023). An infectious disease caused by parasitic trematodes of the genus Schistosoma that colonize human blood vessels and release eggs that can cause granulomatous reactions leading to acute (swimmer's itch or acute schistosomiasis syndrome) or chronic disease. "Similarly, other reports also indicated that ACTB is not the stably expressed gene in mice liver that has undergone fibrosis due to schistosomiasis rather Gapdh showed relatively stable expression in infected as well as healthy mouse liver." (PMID 37145997, 2023).
scleroderma (1 paper, 2023). Scleroderma is a rare autoimmune connective tissue disorder characterized by abnormal hardening of the skin and, sometimes, other organs. "Genes associated with ECM components, such as COL4A1, heparan sulfate proteoglycan 2 (HSPG2), and actin beta (ACTB), as well as phospholipase C gamma 2 (PLCG2), fatty binding protein 4 (FABP4), and galectin 1 (LGALS1), also showed higher expression levels in scleroderma." (PMID 37443817, 2023).
skin cancer (1 paper, 2020). "The extracted data underscore that the somatic mutations in ACTB and ACTG1 do not occur haphazardly across cancers and that the higher frequency observed in two skin cancer and two DLBCL studies merits further investigation." (PMID 32349449, 2020).
squamous cell carcinoma (1 paper, 2023). A carcinoma arising from squamous epithelial cells. "The finding of keratin genes, ACTB, and MMP1 as SPGs is not surprising, as they have been known to be involved in cellular organization functions, particularly in squamous cell carcinoma." (PMID 37371475, 2023).
T-cell deficiency (1 paper, 2023). "If ACTB results were satisfactory, but TREC was not amplified or below the cutoff, then a T-cell deficiency would be suspected and a recall initiated." (PMID 36897914, 2023).
teratoma (1 paper, 2011). A non-seminomatous germ cell tumor characterized by the presence of various tissues which correspond to the different germinal layers (endoderm, mesoderm, and ectoderm). "Bovine-specific primers detected ACTB in both genomic DNA and reverse transcribed cDNA from bovine iPSC-, but not murine ESC-derived, teratomas." (PMID 21912700, 2011).
vascular tumors (1 paper, 2025). "Fusion transcripts involving the FOSB gene on 19q13 with SERPINE1 (7q22), ACTB (7p22) and WWTR1 (3q25) have been detected and may be useful in the differentiation of PMH from other vascular tumors." (PMID 40277775, 2025).
vitiligo (1 paper, 2024). Generalized well circumscribed patches of leukoderma that are generally distributed over symmetric body locations and is due to autoimmune destruction of melanocytes. "Analogously, ACTB was melanocyte lineage-specific genes in vitiligo lesion needle biopsies and to predict the occurrence of perifollicular repigmentation in depigmented macules." (PMID 38754850, 2024).
ZIKV infection (1 paper, 2023). "In addition, we used the same immune-capture approach to determine the level of m6A modification of two cellular transcripts, which were shown to be m6A methylated independent of ZIKV infection, β-actin (ACTB) and Ras GTPase-activating protein-binding protein 2 (G3BP2)." (PMID 38052817, 2023).